MOG (myelin oligodendrocyte glycoprotein)
Diseases named in the same sentence as MOG in open-access papers (continued):
Sharing a sentence is not in itself a finding about the gene and the disease.
cholangiocarcinoma (1 paper, 2024). A carcinoma that arises from the intrahepatic biliary tree (intrahepatic cholangiocarcinoma) or from the junction, or adjacent to the junction, of the right and left hepatic ducts (hilar cholangiocarcinoma). "For instance, the adhesive receptor CR2 for Herpesviridae displayed an upregulation of over 400 times in cholangiocarcinoma (CHOL), while the receptor MOG for the Rubella virus showed an upregulation of over 300 times in kidney chromophobe (KICH) cancer." (PMID 38785923, 2024).
Cirrhosis (1 paper, 2022). A chronic disorder of the liver in which liver tissue becomes scarred and is partially replaced by regenerative nodules and fibrotic tissue resulting in loss of liver function. "Amiloride is used for the treatment of edema caused by heart failure or cirrhosis and has neuroprotective effects, increased myelin oligodendrocyte glycoprotein levels and oligodendrocyte survival, and promoted functional recovery in SCI animal models." (PMID 35883679, 2022).
citrullinemia (1 paper, 2011). Citrullinemia is an autosomal recessively inherited disorder of urea cycle metabolism and ammonia detoxification characterized by elevated concentrations of serum citrulline and ammonia. "Within the group of subjects investigated for CDC, MOG-IgG dependent TCC formation was found in 2/23 (9%) definite NMO, 5/33 (15%) HR-NMO, 8/19 (42%) ADEM, 1/14 (7%) CIS and 1/14 (7%) CTRL (pediatric patient with genetically confirmed citrullinemia with a MOG-IgG serum titer of 1:640)." (PMID 22204662, 2011).
cortical atrophy (1 paper, 2024). "In conclusion, cortical atrophy in myelin oligodendrocyte glycoprotein antibody‐associated disease was characterized by cortical thickness reduction in the adjacent pericalcarine and orbitofrontal regions, with a tendency of temporal thickness reduction in cognitively impaired patients." (PMID 39054631, 2024).
cranial neuropathies (1 paper, 2022). "MOG antibody testing in patients with cranial neuropathies is warranted, and immunotherapy is advocated when the risk of relapse is high." (PMID 36421853, 2022). "Although higher antibody titers and persistently positive serological test results are predictive of disease recurrence, the long-term outcomes of MOG-IgG-positive patients with cranial neuropathies remain largely unknown." (PMID 36421853, 2022).
cystic teratoma (1 paper, 2017). "The association of the MOG antibody inflammatory demyelinating diseases to tumors was reported in the MOG-NMOSD German series; there was one case of mature cystic teratoma and a ganglioneuroma in one patient." (PMID 29064441, 2017).
cysticercosis (1 paper, 2023). "India ink staining, Cysticercosis antibody, the MycoDot test, the FTA-ABS test, aquaporin-4 (AQP4-IgG), myelin oligodendrocyte glycoprotein (MOG) antibody and myelin basic protein (MBP) antibody in the CSF were negative." (PMID 37248444, 2023).
demyelinating polyneuropathy (1 paper, 2024). Polyneuropathy that is characterized by demyelination of axons. "Inclusion criteria were MOG-IgG seropositivity and demyelinating polyneuropathy." (PMID 38930142, 2024).
dyslexia (1 paper, 2013). A learning disorder characterized by an impairment in processing written words. "First, iFC between L.FFG and R.MOG was positively correlated with literacy performance across dyslexia groups (Reading, R2 = 0.49, n = 33, p<0.001; Spelling R2 = 0.14, n = 33, p<0.05)." (PMID 23408984, 2013).
emotional dysregulation (1 paper, 2025). "Thus, dysfunction of the IOG and MOG may lead to clinical symptoms of emotional dysregulation in MDD patients to some extent." (PMID 39905829, 2025).
fungal infection (1 paper, 2015). "Previous fungal infection increased CD4+ T-cell subset in spleen of EAE-mice (EAE+Ca group) and clearly upmodulated the production of many encephalitogenic cytokines by spleen cells stimulated with MOG or heat-killed C. albicans." (PMID 25969836, 2015).
germinoma (1 paper, 2015). A malignant germ cell tumor arising in the central nervous system. "Applying this approach to the MS- and germinoma-derived rIgG demonstrated that none of these antibodies recognized MOG expressed on the surface of the cells." (PMID 26648933, 2015).
Haemophilia A (1 paper, 2025). "This is further underscored by promising results in related models, such as MOG-specific CAR-Treg and MBP-specific TCR-Treg for MS as well as the FVIII-specific CAR-Treg and FVIII-specific TCR-Treg to tolerate rFVIII in Haemophilia A patients." (PMID 41256853, 2025).
herpes simplex encephalitis (1 paper, 2023). Herpes simplex virus encephalitis (HSE) is caused by the infection of the central nervous system by Herpes simplex virus (HSV) that could have a devastating clinical course and a potentially fatal outcome particularly with delay or lack of treatment. "The detection of HSV PCR or HSV IgM in CSF indicated that four patients with anti-NMDAR encephalitis and two patients with MOG-AD were secondary to herpes simplex encephalitis." (PMID 37153594, 2023). "Two of the 48 MOG-AD patients were secondary to herpes simplex encephalitis." (PMID 37153594, 2023).
Herpes simplex infection (1 paper, 2023). "The corresponding KEGG enrichment analysis of the DEGs in MOG-ON revealed that MOG-ON signaling pathways mainly involved Influenza A, Kaposi sarcoma-associated herpesvirus infection, Herpes simplex infection and Toll-like receptor signaling pathway." (PMID 36969199, 2023).
hypertriglyceridemia (1 paper, 2025). A laboratory test result indicating elevated triglyceride concentration in the blood. "Reported adverse events in studies involving NMOSD, MOG antibody-positive patients included an infusion reaction (n = 1), high cholesterol (n = 1), hypertriglyceridemia (n = 1), and tooth infections (n =1)." (PMID 40717732, 2025).
Hyponatremia (1 paper, 2026). An abnormally decreased sodium concentration in the blood. "While serum anti-MOG antibodies were positive, the clinical features, including progressive impairment of consciousness and hyponatremia, were atypical for MOGAD alone, leading to the identification of anti-GFAPα antibodies in the cerebrospinal fluid (CSF)." (PMID 41953873, 2026).
inclusion body myositis (1 paper, 2022). A slowly progressive degenerative inflammatory disorder of skeletal muscles characterized by late onset weakness of specific muscles and distinctive histopathological features. "In the case of inclusion body myositis, MOG-IgG was tested due to an initial concern for a T-cell-mediated inflammatory myopathy with concurrent nonspecific white matter lesions noted on brain MRI." (PMID 35795797, 2022).
infarction (1 paper, 2023). A localised pathological necrosis of tissue resulting from obstruction of the blood supply usually by a thrombus, an embolus, or vascular torsion. "After AIS, BBB breakdown causes OLs antigens such as myelin oligodendrocyte glycoprotein (MOG) and myelin basic protein to leak into the peri-infarction area." (PMID 37962453, 2023).
infectious encephalitis (1 paper, 2023). An acute infectious process that affects the brain tissue. "Our cases had clinical characteristics similar to infectious encephalitis; therefore, they were easily misdiagnosed initially without detection of anti-MOG antibody." (PMID 37520572, 2023).
injury (1 paper, 2014). Damage inflicted on the body as the direct or indirect result of an external force, with or without disruption of structural continuity. "Likewise, oral administration of MOG protected against secondary neurodegeneration in a rat model of acute nerve injury by induction of IL-10 producing myelin-reactive T cells." (PMID 25309322, 2014).
Krabbe disease (1 paper, 2017). A lysosomal disorder that affects the white matter of the central and peripheral nervous systems. "Importantly, DEDA attenuated the psychosine-induced decrease in expression of MBP and MOG as well as vimentin supporting the idea that astrocyte function as well as oligodendrocyte myelination state is altered in Krabbe disease." (PMID 29095858, 2017).
Lafora disease (1 paper, 2024). Lafora disease (LD) is a rare, inherited, severe, progressive myoclonic epilepsy characterized by myoclonus and/or generalized seizures, visual hallucinations (partial occipital seizures), and progressive neurological decline. "The possibly lowered pH, which also occurs in myelin oligodendrocyte glycoprotein antibody disease, an immune-mediated demyelinating disorder of the CNS, may suggest a tendency towards increased anaerobic glycolysis in the epileptic Lafora disease." (PMID 38585668, 2024).
latent syphilis (1 paper, 2024). A stage of syphilis characterized by the serologic evidence of infection by Treponema pallidum without evidence of accompanying signs or symptoms related to the disease. "The coexistence of MOGAD diagnoses and latent syphilis, alongside the identification of antibody reactivity to MOG and T. pallidum, underscores the potential pathomechanistic link between syphilis infection and subsequent autoimmune neuroinflammation." (PMID 39295869, 2024). "We present two cases of patients with diagnoses of latent syphilis and MOGAD with clear-positive MOG-IgG levels according to the International MOGAD Panel proposed criteria, hereby expanding on the existing literature to a total of five reported cases of concurrent syphilis infection and MOGAD." (PMID 39295869, 2024).
liver disease (1 paper, 2025). "Peripheral blood analysis showed significant changes in neurodegeneration markers (NfL, Aβ, p-tau, t-tau, GFAP, MOG) and bile acid profiles, reinforcing the systemic nature of neuroinflammatory processes in liver disease." (PMID 41168263, 2025).
malaria (1 paper, 2014). Malaria is a serious and sometimes fatal disease caused by a parasite that commonly infects a certain type of mosquito which feeds on humans. "Co-cultures showed that malaria-elicited T cells stimulated the proliferation of T cells from MOG-immunized mice." (PMID 25329161, 2014).
Marburg’s disease (1 paper, 2019). "Similarly, more endeavours are needed to better understand the relationship of MDS to other acquired demyelinating syndromes such as ADEM, MOG-EM and Marburg’s disease." (PMID 30819213, 2019).
mastocytosis (1 paper, 2021). A clonal myeloproliferative neoplasm characterized by the proliferation and accumulation of neoplastic mast cells in one or multiple organs or organ systems. "Finally, two patients were positive for both anti-non-allergic and mastocytosis-associated rhinitis (NAMAR) and anti-MOG antibodies." (PMID 34880859, 2021).
motor neuron degeneration (1 paper, 2022). "Myelin oligodendrocyte glycoprotein (MOG), haptoglobin, apolipoprotein C-III (ApoC-III), and apolipoprotein E (ApoE), all failed to recapitulate the motor disability and motor neuron degeneration observed with sALS CSF and ApoB." (PMID 36043141, 2022).
muscular dystrophy (1 paper, 2019). Muscular dystrophy (MD) refers to a group of more than 30 genetic diseases characterized by progressive weakness and degeneration of the skeletal muscles that control movement. "In particular, when the myelin oligodendrocyte glycoprotein (MOG) was coupled to an antibody specific for DEC205 and injected intravenously into mice, the symptoms of experimental allergic encephalomyelitis (EAE), a model system for muscular dystrophy, were drastically suppressed." (PMID 31921144, 2019).
Myotonia (1 paper, 2014). An involuntary and painless delay in the relaxation of skeletal muscle following contraction or electrical stimulation. "By day 36 in the monkey, titers of IgG against conformational epitopes of extracellular MOG were evident, and on day 201, the macaque had an abrupt onset of an unusual form of EAE that included a pronounced arousal-dependent, transient myotonia." (PMID 25303101, 2014).
neurogenic diabetes insipidus (1 paper, 2016). "Of note, two further patients reported events during childhood that are compatible with a first attack of MOG-IgG-positive EM (two episodes of bulbar movement pain, diplopia, and headache at ages 10 and 11 in case 23, and “neurogenic diabetes insipidus” at age 7 in case 22)." (PMID 27793206, 2016).
porphyria (1 paper, 2025). Porphyria is a group of diseases in which substances called porphyrins build up, negatively affecting the skin or nervous system. "In a mouse model for a severe form of porphyria, three oligodendrocyte proteins, MOG, PLP1 and CNP1, emerged through RNA sequencing of the hippocampus, indicating that oligodendrocytes are indeed involved in this group of disorders." (PMID 40114189, 2025).
post-concussion syndrome (1 paper, 2024). The organic and psychogenic disturbances observed after closed head injuries (HEAD INJURIES, CLOSED). "[IL1B on MOG] levels also correlated with the clinical course of a post-concussion syndrome case." (PMID 38559234, 2024).
respiratory infections (1 paper, 2025). "Additionally, three MOG-IgG positive cases presented with acute cerebellar ataxia and preceding respiratory infections, showing mild CSF pleocytosis and normal initial cranial MRI; two of these three cases experienced recurrence during follow-up." (PMID 41321459, 2025).
retinal degeneration (1 paper, 2021). Degeneration of the retina. "Since microglial activation has been associated with retinal degeneration in inflammatory CNS disorders we addressed the question to what extent the cSLO parameters CC and SuA can differentiate MOG- from sham-treated or naïve mice." (PMID 34745138, 2021).
social anxiety disorder (1 paper, 2021). "An rs-fMRI analysis of alterations in baseline cerebral activity of adult patients with social anxiety disorder who had not received pharmacologic treatment found that the amplitude of low-frequency fluctuation of bilateral MOG was significantly increased, indicating changes in brain function." (PMID 33972462, 2021).
Torticollis (1 paper, 2014). Involuntary contractions of the neck musculature resulting in an abnormal posture of or abnormal movements of the head. "The resulting disease was marked by torticollis, unilateral rigid paralysis, forelimb weakness, and high titers of anti-MOG antibody against conformational epitopes of MOG, as well as other signs of atypical EAE." (PMID 25303101, 2014).
trigeminal neuralgia (1 paper, 2023). Trigeminal neuralgia is a nerve disorder that causes a stabbing or electric-shock-like pain in parts of the face. "An ALFF study in patients with classical trigeminal neuralgia (CTN) included 48 patients with CTN found after a single trigger pain, and the ALFF values increased in the bilateral MOG in triggering-5 s and triggering-30 min." (PMID 36814220, 2023).
urinary tract infection (1 paper, 2019). "Despite better motor outcomes among patients with MOG-Ab disease, persistent bladder dysfunction (eg, urgency, hesitancy, incontinence, frequent urinary tract infections) was more common among patients with MOG-Ab disease than patients with AQP4-Ab disease (17 patients [59%] vs 21 patients [48%])." (PMID 31596489, 2019).
Varicella zoster virus infection (1 paper, 2021). "Varicella zoster virus infection-associated cases with MOG/AQP4 antibody associated central nervous system disorders." (PMID 34737756, 2021).
visual agnosia (1 paper, 2020). An inability to recognize or interpret objects by sight. "The MOG belongs to the secondary visual cortex, and damage to the MOG is associated with visual agnosia." (PMID 32935924, 2020).
infection (60 papers, 2011 to 2026). The state of being infected such as from the introduction of a foreign agent such as serum, vaccine, antigenic substance or organism. "Antibodies to NMDAR, GAD, and MOG have been linked to both infection and vaccination, while CASPR-2 and IgLON5 are only associated with infection." (PMID 41311428, 2025). "Myelin oligodendrocyte glycoprotein (MOG) antibody-associated disease (MOGAD) is frequently preceded by infections." (PMID 39295869, 2024). "Here, we transferred naive Tox competent (Tox+/+) or deficient (Tox−/−10) P14 cells into WT or MOG-GP mice one day prior to i.c. infection with rLCMV-GP33." (PMID 33579927, 2021). "The association of MOG-IgG seropositivity with infection and vaccination deserves to be investigated in more detail." (PMID 27802825, 2016). "It is unclear whether this is an unspecific sequel of infection or vaccination or caused by possible immunological cross-reactivity of severe acute respiratory syndrome coronavirus 2 proteins and myelin oligodendrocyte glycoprotein." (PMID 38576796, 2024). "This phenomenon is consistent with previous studies, which indicate that infection may be implicated in the dual positivity of anti-NMDAR/MOG antibodies." (PMID 35837405, 2022). "Similarly, P14 T cells expressed more TOX in MOG-GP than WT mice at 21 days after i.c. infection which was associated with an elevated expression of PD-1, TIGIT, LAG-3 but not TIM-3." (PMID 33579927, 2021). "This aligns with previous studies on MOG-ON, where approximately 37.5% to 67% of MOG antibody-positive patients had a history of infection before onset." (PMID 41235231, 2025). "The MOG-OPN group had a higher proportion of participants with previous infection (62.5% vs. 8.0%; P = 0.004), and mycophenolate mofetil use (37.5% vs. 4.0%; P = 0.036)." (PMID 41235231, 2025). "Circulating MOG-IgG antibodies are thought to arise through mechanisms such as molecular mimicry or bystander activation, potentially triggered by infections or environmental factors." (PMID 41153632, 2025). "Comparing MOG-ON and AQP4-ON patients, MOG-ON patients were more likely to have a recent infection before ON onset (73.1% vs. 30%; p = 0.007) and had better peak and post-treatment visual acuity (p = 0.01; p < 0.001)." (PMID 38988608, 2024). "Infections, molecular mimicry, and MOG peptide presentation can promote the activation of self-reactive T cells." (PMID 39408955, 2024). "Yet, molecular evidence linking infection to the generation of a MOG-specific B cell response is missing." (PMID 39295869, 2024). "Next, we analysed the predictive role of antibody response to SARS-CoV-2 and other coronaviruses, acute infections (SARS-CoV-2 or other infections), inflammatory demyelination, sex and age on MOG antibody classes using ordinal regression analysis." (PMID 38576796, 2024). "Triggered by infection, vaccination, or other stimuli, these MOG-reactive T cells are activated and penetrate the blood–brain barrier (BBB) into the CNS and aggregate at the perivascular space of the meninges and parenchyma (perivascular cuffing)." (PMID 37545724, 2023). "Further, most patients with isolated MOG-IgA presented clinical attacks after recent infection or vaccination (7/11 [64%])." (PMID 37548987, 2023). "In MOG-IgG+ ADEM patients preceding infection was present in 70% (12/17, including three patients with vaccinations)." (PMID 36925938, 2023). "6-week-old mice of the GFAP:GP, aCD20-GFAP:GP, and STOP:GP conditions were treated with TAM (6 weeks post-infection) and sacrificed seven days after initial TAM administration, while mice of MOG:GP were sacrificed 47 days after initial infection." (PMID 36695896, 2023). "Limited studies in experimental allergic encephalitis (EAE) models demonstrated that prior infection with Hp induced Foxp3+Treg cell upregulation and inhibition of MOG specific Th1 and Th17 responses." (PMID 37304259, 2023).